SHC2 (SHC adaptor protein 2)
Description:
Signaling adapter that couples activated growth factor receptors to signaling pathway in neurons. Involved in the signal transduction pathways of neurotrophin-activated Trk receptors in cortical neurons (By similarity).
Synonyms: SCK; SHCB; SLI
Tractability: Antibody: its Gene Ontology location is reachable by antibodies, with medium confidence.
Target class: Other cytosolic protein
Gene: Protein-coding gene on chromosome 19 (416,589 to 461,100, reverse strand). Ensembl gene ENSG00000129946.
Subcellular location (Human Protein Atlas): Cytosol
Pathways (Reactome):
Signal Transduction: RAF/MAP kinase cascade; Signalling to RAS; VEGFA-VEGFR2 Pathway
Gene Ontology:
Molecular function: protein binding; receptor tyrosine kinase binding
Biological process: cell surface receptor protein tyrosine kinase signaling pathway; intracellular signal transduction
Cellular component: cytosol; plasma membrane
Genetic constraint (gnomAD): Loss-of-function variants: 61 observed, 50.87 expected, observed/expected ratio (o/e) 1.2, 90% interval 0.98 to 1.48. The upper end of that interval is the gene's LOEUF score, 1.48, which puts it in group 6 of 6, group 1 being the genes least tolerant of losing a copy. Missense variants: 822 observed, 661.92 expected, observed/expected ratio (o/e) 1.24, 90% interval 1.17 to 1.32. Synonymous variants: 349 observed, 295.75 expected, observed/expected ratio (o/e) 1.18, 90% interval 1.08 to 1.29.
Diseases named in the same sentence as SHC2 in open-access papers:
SHC2 is named in the same sentence as 28 diseases in open-access papers, as found by Europe PMC text mining. Sharing a sentence is not in itself a finding about the gene and the disease. The quoted sentences say what the papers report.
breast carcinoma (2 papers, 2021 to 2024). "The result indicated that the DSVs in SNTG2, PCMT1, DACT2, CBX3, ATP11A, and SHC2 were associated with breast cancer." (PMID 33431054, 2021). "Further studies may be focused on exploring how SHC2 CNV loss can impact the prognosis of breast cancer metastasis." (PMID 38791477, 2024). "However, further research is needed to analyze the mechanism of the genes SHC2, KRT6B, and SFRP2 in breast cancer liver metastasis." (PMID 38791477, 2024).
glioma (2 papers, 2023). A benign or malignant brain and spinal cord tumor that arises from glial cells (astrocytes, oligodendrocytes, ependymal cells). "SHC2 and GRB14 are both linked to metabolism-linked cellular growth, and belong to SHC and GRB families; other members have been annotated as glioma pathway members [KEGG pathways." (PMID 36834486, 2023).
breast tumor (1 paper, 2024). "SHC2, LPL, PCK1, and KRT6B were all under-expressed, and only SFRP2 was highly expressed in the breast tumor." (PMID 38791477, 2024).
cerebellar ataxia (1 paper, 2011). A neurological syndrome characterized by clumsy and uncoordinated movement of the limbs, trunk, and cranial muscles. "Finally, we estimated the copy number loss of SHC2 in each patient and tested it for correlation with the phenotype at sampling (MSA-P vs. MSA-C) and at the onset of MSA (parkinsonism vs. cerebellar ataxia with/without autonomic failure) by chi-square test or Fisher's exact probability test." (PMID 21658278, 2011).
invasive breast carcinoma (1 paper, 2024). A carcinoma that infiltrates the breast parenchyma. "For the five genes (LPL, PCK1, KRT6B, SFRP2, SHC2) that were differentially expressed between the datasets, we analyzed the alterations in metastatic breast cancer and invasive breast cancer genetic profiles." (PMID 38791477, 2024).
pancreatic ductal adenocarcinoma (1 paper, 2022). An infiltrating adenocarcinoma that arises from the epithelial cells of the pancreas. "CD95-mediated Sck/Shc2 activation is essential for pancreatic ductal adenocarcinoma growth and metastasis." (PMID 36505426, 2022).
tumor (5 papers, 2021 to 2025). "Apart from the PI3K/AKT pathway (CDC37, IL6R), Epidermal-Mesenchymal transition (IL6R, SHC2), tumour metastasis and T1/T2 activation are highlighted (DLL1, STAT4, IL6R)." (PMID 36834486, 2023). "The majority of DEGs related to this pathway (ITGAV, KDR, VEGFB, AKT1, VEGFA) were downregulated in tumor cells except for HSBP1 and SHC2." (PMID 39245631, 2025). "We observed major genetic alterations in PCK1, SHC2, and KRT6B, emphasizing the role of these genes in tumor behavior modification as well as the response to treatment." (PMID 38791477, 2024). "FGF17, natriuretic peptide A (NPPA), SHC2, and WAP, follistatin/kazal, immunoglobulin, kunitz, and netrin domain containing 1 (WFIKKN1) was not expressed or at a minimal level in tumor tissues." (PMID 34335699, 2021).
cancer (4 papers, 2021 to 2024). A tumor composed of atypical neoplastic, often pleomorphic cells that invade other tissues. "Previous research has found that SHC2 is coding for the SHC-coding transforming protein 2, which associates with the cancer’s start and later progression." (PMID 38791477, 2024).
neurologic disease (1 paper, 2011). "None of the CNVs around SHC2 described in the Database of Genomic Variants were associated with human neurologic disease." (PMID 21658278, 2011).
SHC2 also shares sentences with these, for which no sentence is quoted: glioblastoma (2 papers); rhabdomyolysis (2); bladder cancer (1); cardiovascular disease (1); cerebral infarction (1); congenital myopathies (1); diabetes (1); diabetic nephropathy (1); dystrophin deficiency (1); end-stage renal disease (1); endometrial cancer (1); multiple system atrophy (1); myopathy (1); Parkinsonism (1); Pompe disease (1); prolactinoma (1); renal failure (1); type II diabetes (1); viral infections (1).